CCR7 (C-C motif chemokine receptor 7)
Diseases named in the same sentence as CCR7 in open-access papers (continued):
Sharing a sentence is not in itself a finding about the gene and the disease.
lymphedema (2 papers, 2011 to 2023). Excess fluid collection in tissues, causing swelling. "In the present study, CCR7+ expression in CD8+ T cells was downregulated in post-LVA compared with that in lymphedema." (PMID 37250774, 2023). "In contrast to CCR7 expression in CD4+ T cells, the number of CCR7+CD8+ cells was significantly decreased, whereas that of CCR7−CD8+ cells was significantly increased in post-LVA compared with that in lymphedema." (PMID 37250774, 2023).
lymphoproliferative disorders (2 papers, 2013 to 2021). "As such, in most lymphoproliferative disorders, CCR7 expression correlates with nodal or spleen involvement." (PMID 34778050, 2021). "CCR7 is expressed in different primary lymphoproliferative disorders as we and others have previously demonstrated." (PMID 24305507, 2013). "Our results show that tumor cells from CLL and MCL patients consistently express CCR7 on the cell surface and at high density, compared to other lymphoproliferative syndromes." (PMID 24305507, 2013). "Therefore, the blockage of CCR7-mediated migration might represent a new therapeutic approach for the treatment of certain lymphoproliferative disorders." (PMID 24305507, 2013). "In summary our results support that anti-CCR7 immunotherapy might be an option for the treatment of MCL and other CCR7+ lymphoproliferative disorders." (PMID 24305507, 2013).
mesothelioma (2 papers, 2017 to 2020). A usually malignant and aggressive neoplasm of the mesothelium which is often associated with exposure to asbestos. "This hypothesis was supported by the CCR7 measurements that revealed a significant increase in the abundance of this receptor (a major actor in the DC migration to the lymphatics) on DCs exposed to PDT-killed mesothelioma cells Ab1 and Ab12 (vs. LPS-treated DC)." (PMID 32120810, 2020).
myocardial infarction (2 papers, 2012 to 2023). Gross necrosis of the myocardium, as a result of interruption of the blood supply to the area, as in coronary thrombosis. "Animal characteristics and echocardiographic measurements in CCR7 deficient and wild-type mice 6 weeks after sham operation or myocardial infarction." (PMID 22427939, 2012). "Animal characteristics and echocardiographic measurements in CCR7 deficient and wild-type mice 1 week after sham operation or myocardial infarction." (PMID 22427939, 2012). "Here, we elaborated this hypothesis by clinical studies in patients with chronic HF and in patients with acute HF following myocardial infarction (MI), as well as in studies of CCR7 deficient mice in an animal model of post-MI HF." (PMID 22427939, 2012).
myocardial ischemia (2 papers, 2012 to 2022). A disorder of cardiac function caused by insufficient blood flow to the muscle tissue of the heart. "Altogether, this suggests an important role of CD4+CCR7+ T cells during early reperfusion and potentially myocardial ischemia/reperfusion injury." (PMID 23077561, 2012).
oral cancer (2 papers, 2019 to 2022). "Another oral cancer, squamous carcinoma of the tonsils, showed that at high CCR7 levels, patients had a significant (p < 0.001) increase in cervical node metastasis, relapse-free (p = 0.0175), overall and disease-free survival rates p = 0.0062." (PMID 35203305, 2022). "In general, high levels of CCR7 predict poor prognosis for patients with oral cancers." (PMID 35203305, 2022). "The role of CCR7 immunoexpression to predict cervical lymph node metastasis of oral SCC has been previously reported, so our results confirm the predictive utility of this marker in oral cancer." (PMID 31011147, 2019).
parasite infection (2 papers, 2015 to 2023). "From this, we identified 26 common DEGs downregulated in Tr1 cells from both parasitic diseases, including Ccr7, Tcf7, and Bcl6, as well as 29 upregulated DEGs, including Il10, Havcr2, Prdm1, Ccr2, Ccr5, Maf, and Lag3." (PMID 37917177, 2023). "Parasites lacking ASP5 show a considerable loss of this capacity, which correlates with the down-regulation of CCR7 observed in the RNA seq data upon Δasp5 type I and type II parasite infection." (PMID 26473595, 2015).
perihilar cholangiocarcinoma (2 papers, 2023 to 2025). "The association between CCR7 expression and clinicopathological features and EMT status was examined via the immunohistochemical staining of tumor sections from 181 patients with perihilar cholangiocarcinoma." (PMID 36980764, 2023).
pertussis (2 papers, 2016 to 2024). A contagious bacterial respiratory infection caused by Bordetella pertussis. "OMVs were benchmarked against licensed vaccines, including Bexsero and whole cell pertussis formulations, with respect to Th-polarizing cytokine and prostaglandin E2 production, as well as cell surface activation markers (HLA-DR, CD86, and CCR7)." (PMID 28008331, 2016).
polyp (2 papers, 2016). A usually exophytic mass attached to the underlying tissue by a broad base or a thin stalk. "Our results demonstrated that most IL-21+CD8+ T cells expressed high CD45RO levels but minimal CD62L and CCR7 levels, exhibiting an effector memory phenotype in polyp tissues." (PMID 27468819, 2016).
pulmonary tuberculosis (2 papers, 2020 to 2021). A bacterial infection that affects the lungs and is caused by Mycobacterium tuberculosis. "CCR7 ligation by CCL19 and CCL21 is vital for the positioning of T cells and dendritic cells of secondary lymphoid tissues, and CCR7-deficient mice, which are deficient in CCL19 and CCL21 signaling, are fully capable to control pulmonary tuberculosis." (PMID 33686954, 2021).
renal fibrosis (2 papers, 2021 to 2026). A final common manifestation of a wide variety of chronic kidney diseases characterized by glomerulosclerosis and tubulointerstitial fibrosis. "For example, in a mouse model of kidney fibrosis, CCR7+ fibrocytes help induce renal fibrosis following ureteral obstruction." (PMID 41596210, 2026). "Together, above results elucidated that inhibiting the drainage of CCR7+ cells greatly alleviated chronic rejection and renal fibrosis." (PMID 34956231, 2021).
skin infection (2 papers, 2018 to 2023). An inflammatory process affecting the skin, caused by bacteria, viruses, parasites, or fungi. "CCR7-bearing inflammatory monocytes carried L. donovani parasites via enhanced migration from the skin infection site to the viscera of malnourished mice." (PMID 36630476, 2023). "PGE2 production at the site of skin infection was increased in the malnourished host and led to increased CCR7 expression on inflammatory monocytes." (PMID 36630476, 2023). "PGE2 production, which was increased at the site of skin infection, increased monocyte CCR7 expression and promoted CCR7-related monocyte-mediated early parasite dissemination in malnourished mice." (PMID 36630476, 2023). "In models of acute lung and skin infection, T cells egress from inflamed peripheral tissue in a CCR7-dependent manner, such that CD4+ T cells accumulate in epithelial tissue of CCR7−/− mice in an age-dependent manner." (PMID 30498499, 2018). "To evaluate a causal role of CCR7 in the monocyte-mediated trafficking of parasites from the skin infection site to the spleen, we knocked down the expression of CCR7 in monocytes by siRNA (p<0.0001) and transferred these cells to the dermal infection site in MN mice." (PMID 36630476, 2023).
thymic lymphomas (2 papers, 2014 to 2015). "Furthermore, by gating of the CD11c+ DCs cell population using flow cytometry analysis, we confirmed that the Ia, CD86, CD80, CCR7, CD40 and IL-12 proteins of CD11+ DCs were all down-regulated in thymic lymphomas." (PMID 25923834, 2015).
tongue cancer (2 papers, 2022 to 2023). A malignant neoplasm affecting the tongue. "In this study, CCR7 tissue immunostaining was high in tongue cancer and was significantly associated with male tongue cancer patients compared to females." (PMID 35203305, 2022). "Therefore, this study suggests that the evaluation of CCR7 staining level by MNN may be useful in diagnosing the presence of cervical lymph node metastasis in tongue cancer." (PMID 36307918, 2023). "The learning model developed demonstrated the usefulness of CCR7 immunohistochemistry for the diagnosis of cervical lymph node metastasis in tongue cancer." (PMID 36307918, 2023).
ulcerative colitis (2 papers, 2022 to 2026). An inflammatory bowel disease involving the mucosal surface of the large intestine and rectum. "Specifically, there is a potential role for CCR7 in colorectal cancer progression based on the overexpression of CCR7 ligand CCL21 observed in the inflammatory bowel disease, ulcerative colitis." (PMID 35203305, 2022).
uveal melanoma (2 papers, 2022 to 2024). A melanoma derived from melanocytes of the uveal tract. "Another study on uveal melanoma on paraffin-embedded tissue samples confirmed expression of CCR7 and CXCR4 and found expression of CCR10, primarily in the cytoplasm, for each chemokine receptor; CCL19 demonstrated a moderate expression." (PMID 35203305, 2022). "Overall, data linked CCR7 expression to liver metastasis of uveal melanoma, but, as with the earlier studies, it is not clear that CCR7 is functional." (PMID 35203305, 2022). "Primary tumor uveal melanoma cells express CXC Motif Chemokine Receptor 4 (CXCR4) and C-C Chemokine Receptor 7 (CCR7)." (PMID 38732371, 2024). "Analysis of primary uveal melanoma cell lines found elevated expression of CCR7 and CXCR4, although metastatic cell lines had no change in these receptors, and similar results were observed in a nude mouse model." (PMID 35203305, 2022).
visceral leishmaniasis (2 papers, 2018 to 2023). A severe form of leishmaniasis characterized by irregular bouts of fever, substantial weight loss, swelling of the spleen and liver, and anemia (which may be serious). "In visceral leishmaniasis (VL), cellular immunosuppression is mediated by impaired DC migration due to the decreased chemokine secretion by endothelium and to the reduced DCs CCR7 expression." (PMID 29867949, 2018).
vitiligo (2 papers, 2022 to 2024). Generalized well circumscribed patches of leukoderma that are generally distributed over symmetric body locations and is due to autoimmune destruction of melanocytes. "Another chemokine ligand CCL19, which attracts CCR7+ cells, was involved in the development of vitiligo during the treatment of advanced melanoma by immune checkpoint inhibitors." (PMID 35096274, 2022). "Highly significant changes in the expression of recruitment and homing-related genes CCL19, CCR7 and CXCL8 were found in growing feathers of vitiligo-expressing Smyth chickens (P < 0.0001)." (PMID 38720888, 2024). "Chemokine ligand-receptor pairs that guide the migration of Tregs include CCL1 and CCR8, CCL21 and CCR7, and CCL22 with its receptor CCR4, while studies on vitiligo skin samples only revealed a significant reduction in CCL22 expression." (PMID 35096274, 2022).
abdominal aortic aneurysm (1 paper, 2021). Enlargement and ballooning of the vessel that supplies arterial blood to the abdomen, pelvis and legs. "Although there is no direct evidence that CCR7 is associated with IA, the expression of CCR7 is significantly downregulated in abdominal aortic aneurysm." (PMID 34485395, 2021).
abortion (1 paper, 2024). the ending of pregnancy by removing a fetus or embryo before it can survive outside the uterus. "In Maturation stages of T cell group, Naive CD8br %T cell, CD4 on CD45RA+ CD4+ and CCR7 on naive CD4+ were negatively associated with abortion (OR < 1), while CCR7 on naive CD8br was positively associated with abortion (OR > 1)." (PMID 39388432, 2024). "Conversely, our study also identified negative causal associations in certain T cell maturation stages, including Naive CD8br %T cells, CD4 on CD45RA+ CD4+, and CCR7 on naive CD4+, implying a protective role against abortion." (PMID 39388432, 2024).
acute leukemia (1 paper, 2021). A clonal (malignant) hematopoietic disorder with an acute onset, affecting the bone marrow and the peripheral blood. "Moreover, a clinical research indicated that CCR7 was highly expressed in adult acute leukemia cells, and the expression of CCR7 was related to extramedullary infiltration in ALL." (PMID 33743810, 2021).
adenoma (1 paper, 2021). A neoplasm arising from the epithelium. "Aldosterone-producing adenomas showed lower CCR7 protein levels (H-score 1.3 ± 1.0) compared to non-functioning (2.4 ± 0.5) and cortisol-producing adenomas (2.3 ± 0.6), whereas protein expression was variable in ACC (1.8 ± 0.8)." (PMID 34830848, 2021). "Looking at different adrenocortical adenomas, non-functioning and cortisol-producing adenomas showed the highest CCR7 expression both for mRNA and protein level in contrast to aldosterone-producing adenomas." (PMID 34830848, 2021). "Aldosterone-producing adenomas showed lower staining intensities for CCR7 compared to non-functioning and cortisol-producing adenomas." (PMID 34830848, 2021).
adrenocortical adenomas (1 paper, 2021). "Here, we investigated the expression of CCR7 in normal adrenal glands, adrenocortical adenomas, and adrenocortical carcinomas." (PMID 34830848, 2021). "We, therefore, set out to investigate whether the chemokine receptor CCR7 plays a role in the adrenal gland, adrenal adenomas, and especially ACC." (PMID 34830848, 2021). "In ACC, however, we observed lower mRNA levels of CCR7 compared to normal adrenals and adrenocortical adenomas and could confirm this finding in an independent cohort using publicly available datasets." (PMID 34830848, 2021). "mRNA levels of CCR7 were not significantly different between ACCs, normal adrenals, and adrenocortical adenomas." (PMID 34830848, 2021). "Therefore, CCR7 is most likely not involved or dependent on hormone production of different adrenal adenomas." (PMID 34830848, 2021).
Adrenocortical Carcinoma (1 paper, 2021). "However, CCR7 protein or mRNA expression did not significantly influence patient survival in adrenocortical carcinoma, but it could play a role in adrenocortical homeostasis." (PMID 34830848, 2021).
Adrenocortical Tumors (1 paper, 2021). "No data exist on the expression of CCR7 in adrenocortical tumors." (PMID 34830848, 2021).
Airway obstruction (1 paper, 2015). Obstruction of conducting airways of the lung. "The possible underlying mechanism that links reduced myeloid DC CCR7+ expression levels and airway obstruction may be that impaired homing of myeloid DCs to the lymph nodes results in the accumulation of myeloid DCs in the airways." (PMID 25338516, 2015).
aortic aneurysm (1 paper, 2024). A ruptured aneurysm located in the wall of the proximal portion of the descending aorta proceeding from the arch of the aorta. "High proportions of CCR7+ cells were observed in active patients with BD73 and aortic aneurysm." (PMID 38785203, 2024).
aortic stenosis (1 paper, 2022). Aortic valve stenosis is a aortic valve disease caused by the incomplete opening of the aortic valve. "Another study suggested that CCL21/CCR7 interactions was involved in left ventricular remodeling during pressure overload in patients with aortic stenosis." (PMID 36159993, 2022).
appendicitis (1 paper, 2023). Acute inflammation of the vermiform appendix. "In all tissue layers of the appendix combined, a trend towards decreased frequencies of naïve CD4+ T cells (Tn; CCR7+CD45RA+) was observed in children with complex compared to simple appendicitis." (PMID 38239362, 2023).
atopic asthma (1 paper, 2018). An asthma that is characterized by symptoms that are triggered by an allergic reaction caused by inhaled allergens such as dust mite allergen, pet dander, pollen and mold. "We thus concluded that the increase of circulating CCR7+ memory CD4+ T cells is a common feature of adult atopic asthma patients." (PMID 29507584, 2018). "Compiled data from atopic asthma patients and control subjects indicated that atopic asthma patients have more CD45RA−CD45RO+CCR7+ CD4+ T cells than control subjects (left)." (PMID 29507584, 2018). "We thus concluded that adult atopic asthma patients have increased CCR4+ CD4+ T cells in their blood and this increase is mainly due to the increase of CCR4+CD45RA−CD45RO+CCR7+ CD4+ T cells." (PMID 29507584, 2018). "In this study, however, we further found that atopic asthma patients have a significant increase in memory CD4+ T cells that express CCR7, but not CCR7− memory CD4+ T cells." (PMID 29507584, 2018). "Furthermore, leukotriene inhibitors did not alter the percentage of CCR7+ memory CD4+ T cells in the blood of adult atopic asthma patients." (PMID 29507584, 2018). "CCR4+CCR7+ memory, but not CCR4+CCR7− memory, α4+, and CTLA4+ CD4+ T cells in patients show significant clinical implications in atopic asthma." (PMID 29507584, 2018). "Taken together, we concluded that the frequency of CCR4+ CD4+ T cells, particularly CCR4+CD45RA−CD45RO+CCR7+ CD4+ T cells, varies among atopic asthma subtypes, but are not significantly influenced by corticosteroid or leukotriene inhibitor treatments." (PMID 29507584, 2018). "Therefore, we concluded that adult atopic asthma patients have an increase of circulating CD45RA−CD45RO+CCR7+ T cells, but not CD45RA−CD45RO+CCR7− or CD45RA+CD45RO− CD4+ T cells." (PMID 29507584, 2018).
autoimmune thrombocytopenia (1 paper, 2025). An autoimmune form of thrombocytopenia. "Together, these data define APOO as a metabolic-transcriptional checkpoint governing CCR7+CD4+ T cell fate, whose repression fosters dysfunctional differentiation and immune imbalance in autoimmune thrombocytopenia." (PMID 41244589, 2025).
Ba (1 paper, 2022). "Particularly, we previously published results showing that Ba infection induces DCs maturation, as evidenced by the up-regulation of CD86, CD80, CCR7, CD83, MHC-II, MHC-I and CD40 at 24 h post-infection." (PMID 36441810, 2022).
Behcet disease (1 paper, 2025). A chronic, relapsing, multisystemic vasculitis characterized by mucocutaneous lesions, as well as articular, vascular, ocular and central nervous system manifestations. "Furthermore, through multiomics data analysis and machine learning techniques, researchers identified CD247, CD2, and CCR7 as diagnostic biomarkers for AAA in Behcet's disease patients and developed a nomogram model for diagnosis." (PMID 40995065, 2025).
bladder tumor (1 paper, 2024). "Upregulation and de novo expression of chemokine receptors on BCa cells, including CCR5, CXCR2, and CCR7, is often seen during tumorigenesis and directly modulates bladder tumor growth, survival, and EMT." (PMID 39409924, 2024). "Immunohistochemistry (IHC) staining of human bladder tumor samples revealed elevated expression of CCR7 in BCa, with 64.52% of the cohort exhibiting high levels of CCR7." (PMID 39409924, 2024).
Blau syndrome (1 paper, 2020). Blau syndrome (BS) is a rare systemic inflammatory disease characterized by early onset granulomatous arthritis, uveitis and skin rash. "We showed that T cells from patients with Blau syndrome produce excessive IL-17 and over express CCR7 upon TCR-ligation, thereby paralleling the hyper-pathogenic T cell responses found in Nod2−/− mice." (PMID 33106495, 2020). "As with Nod2−/− memory T cells in mice, which showed increased expression of Ccr7 in response to TCR-ligation, CD3/CD28 stimulation also increased expression of CCR7 on CD4+ T cells similarly in both the patients with Blau syndrome compared to healthy controls." (PMID 33106495, 2020). "Interestingly, CD4+ T cells from two Blau syndrome patients show elevated IL-17 and increased CCR7." (PMID 33106495, 2020).
celiac disease (1 paper, 2024). An autoimmune genetic disorder with an unknown pattern of inheritance that primarily affects the digestive tract. "Further, children with a double diagnosis had a higher percentage of CCR7+IgD− relative to celiac disease-diagnosed children (P = 0.032)." (PMID 38134245, 2024).